HDAC1 (histone deacetylase 1)
Diseases named in the same sentence as HDAC1 in open-access papers (continued):
Sharing a sentence is not in itself a finding about the gene and the disease.
cancer (continued). "Aberrant HDAC1 activity has been linked to various diseases, especially cancer." (PMID 39199296, 2024). "Both SIRT1 and HDAC1 have been implicated in cancer development." (PMID 37667739, 2023). "The dysregulation of HDAC1, a chromatin modifier, may cause harmful effects on cell fate and function, which could lead to cancer." (PMID 36925653, 2023). "PIAS4 is involved in the sumoylation of HDAC1, an essential epigenetic regulator belonging to a conserved family of deacetylases that may be implicated in cancer progression." (PMID 35887358, 2022). "In summary, our results demonstrate that transcriptional activation of HDAC1 is the primary mechanism underlying SOX4 supporting cancer stemness and this finding suggests that inhibition of HDAC1 would be an effective therapeutic strategy for human cancer with aberrant SOX4 upregulation." (PMID 33482915, 2021). "HDAC1 is highly expressed in many human tumors, and its overexpression is associated with poor outcomes and tumor progression, thereby identifying this epigenetic eraser as a promising target for cancer therapy." (PMID 33922029, 2021). "LIPUS may be used as a HDAC1 activator to alleviate some adverse effects in normal tissues caused by clinical application of HDAC inhibitor in cancer therapy." (PMID 31322450, 2019). "Unsurprisingly, therefore, Sin3/HDAC1 have been implicated in the regulation of numerous cellular processes, including mammalian development, maintenance of pluripotency, cell cycle regulation and diseases such as cancer." (PMID 30552170, 2018). "Taken together, these findings suggest that HDAC1 may be a good diagnostic and prognostic marker for some types of cancer." (PMID 28424407, 2017). "It is reported that HDAC1 is associated with the development of radioresistance in cancer cells." (PMID 26521947, 2015). "It remains to be further investigated whether HDAC1 acetylation, whose modification negatively regulates HDAC1-associated corepressor complex activity, is downregulated in cancer models." (PMID 25950477, 2015). "The fact that the NuRD complex contains MTA2, which is associated with cancer metastasis, provides further evidence that HDAC1 may play a role in cancer development." (PMID 17022812, 2006). "Specifically, HDAC1 is linked with cell growth, a hallmark of cancer formation." (PMID 17022812, 2006). "The outcomes from this study might be useful for the identification and development of repurposed HDAC1 inhibitors with promising affinity towards the target protein and acceptable efficacy in the treatment of diseases associated with HDAC1, including cancer and neurodegenerative diseases." (PMID 39752394, 2025). "Of note, HDAC1, -2, -3, -4, -5, -6 and -7 appear to be most crucial for the proliferation, aggressiveness and apoptosis resistance of cancer cells, and high expression levels of these HDACs in tumours are associated with a poor prognosis for the cancer patients." (PMID 35626663, 2022). "Altogether, our in vitro and in vivo data indicate that the ERBB2 gene is a novel MBP-1 target, and immunohistochemistry analysis of primary tumors suggests that the concomitant high expression of MBP-1 and HDAC1 may be considered a diagnostic marker of cancer progression for breast IDC." (PMID 23421821, 2013). "Targeting HDAC1 through repurposed drugs is a promising strategy for therapeutic development in modern drug discovery against cancer and neurodegeneration." (PMID 39752394, 2025). "Over‐expression of different HDACs (HDAC1, 2, 3 and 6) has been confirmed earlier in different cancers." (PMID 40159638, 2025). "Another study showed that CREPT disrupts histone deacetylase 1 (HDAC1) function in cancer and promotes the expression of other oncogenes." (PMID 40723282, 2025).
cancer (continued). "These stable interactions highlight Alectinib’s promise as a potential HDAC1 inhibitor for cancer therapy, underscoring its therapeutic relevance." (PMID 39752394, 2025). "Among various cancer types, histone deacetylases (HDACs), particularly histone deacetylase 1 (HDAC1), are frequently overexpressed." (PMID 40475010, 2025). "In the PC vs para-PC network, key hub proteins, such as SRC, PTEN, and HDAC1—known regulators of cancer signaling and epigenetic control—were prominent." (PMID 40358702, 2025). "Second, emerging evidence reveals their critical role in shaping the tumor microenvironment (TME)—HDAC1/2 suppress antigen presentation machinery in cancer cells, while HDAC3 promotes immunosuppressive macrophage polarization." (PMID 41267925, 2025). "Studies have confirmed that HDAC1 inhibition reinstated CCL5-driven CD8+ T cell recruitment in cancer." (PMID 40475010, 2025). "These synthetic mutants and the cancer mutants, therefore, exploit not only the active site tunnel of HDAC1, but also its peripheral regions." (PMID 39939763, 2025). "Studies in cancer cells have shown that HDAC1 represses both p21WAF1/CIP1 and Bax, contributing to uncontrolled cell proliferation." (PMID 40581884, 2025). "Although vorinostat is a well-established HDAC1 inhibitor, its resistance in cancer cells has necessitated the investigation of anti-leukemic phytochemicals as potential alternative therapeutic agents." (PMID 40696057, 2025). "Taken together, our findings establish SDFZ‐8 as a novel HDAC1 inhibitor that concurrently targets tumor cells and immune evasion mechanisms, providing a rational combinatorial strategy to enhance cancer immunotherapy efficacy." (PMID 41267925, 2025). "This study bridges a key gap in HDAC‐targeted therapy by demonstrating that precision HDAC1 inhibition can simultaneously target cancer cells and overcome immune evasion, offering a transformative paradigm for small‐molecule cancer immunotherapy." (PMID 41267925, 2025). "The HDAC1 levels are elevated in several cancers such as colorectal, lung, gastric, and bladder cancers." (PMID 40581884, 2025). "To investigate the potential of HDAC1-3 inhibitions in cancer therapy, we analyzed the expression and prognostic value of HDAC1, 2, and 3 in various cancers using the GEPIA2 web tool based on The Cancer Genome Atlas database." (PMID 39891718, 2025). "Lactylation involves the accumulation of lactate during cellular metabolism, altering lysine residues on histones, and plays a pivotal role in cancer development.[18a] HDAC1 has been identified as an enzyme that removes acetylation from histones." (PMID 39888307, 2025). "Cryo-electron microscopy analysis of two distinct KBTBD4 cancer mutants bound to LSD1–HDAC1–CoREST reveals that a KBTBD4 homodimer asymmetrically engages HDAC1 with two KELCH-repeat β-propeller domains." (PMID 39939763, 2025). "As a purely in silico investigation, additional in vitro and in vivo studies are essential to confirm Alectinib’s HDAC1 inhibitory activity, cytotoxicity, and selectivity in cancer models." (PMID 39752394, 2025). "Modulation of enhancer function by IKAROS and HDAC1, represses the transcription of genes that regulate cancer pathways." (PMID 40555735, 2025). "HDAC1 (histone deacetylase 1) is known to promote tumor growth in various cancers by regulating chromatin structure through deacetylation, thus influencing gene expression." (PMID 39723246, 2024). "HDAC1 inhibition in cancer cells is reported to induce cell cycle arrest and suppress invasion and migration." (PMID 38709067, 2024). "Examination of cancer-specific pathways in the HCC tumors showed that HDAC1-Sp5 pathway is increased, while hepatocyte markers are reduced." (PMID 39001363, 2024). "The progression of cancer by S1P can be related to the regulation of HDAC1/2 enzymes and subsequent modulation of gene transcription to promote cancer." (PMID 38419070, 2024).
cancer (continued). "Targeting HDAC1 to modulate IGF1R SUMOylation holds significant implications for cancer research and therapy." (PMID 39723246, 2024). "The association of upregulation of HDAC5 with sensitivity to multiple kinases and of HDAC1 with dasatinib sensitivity is unexpected, based on frequently reported clinical benefits of inhibition of their products in cancer treatment." (PMID 38369747, 2024). "Tango Therapeutics generated a STK11-deleted MC38 mouse cancer model and, through an in vivo CRISPR screening platform, found that HDAC1 is a key target mediating immune evasion in STK11-deficient tumors." (PMID 39655075, 2024). "Increased maspin expression in cancer cells reportedly induces cell cycle arrest and apoptosis, promotes drug sensitivity, and inhibits HDAC1 activity, which play crucial roles in cancer progression and development." (PMID 39272867, 2024). "The results indicated that KDM1A and KDM5A significantly interact with HDAC1/2, which plays a critical role in cancer by regulating gene expression through histone deacetylation, thereby influencing cell proliferation, apoptosis, and metastasis." (PMID 39239542, 2024). "Its expression declined in both intrinsic and acquired cisplatin-resistant HNSCC cells, indicating an intricate role of HDAC1 in the cancer microenvironment." (PMID 38702756, 2024). "Recent studies have begun exploring its potential in cancer therapy, particularly its impact on histone deacetylase 1 (HDAC1)." (PMID 39723246, 2024). "HDAC1 is frequently encountered in high-grade HCC; elevated HDAC1 expression is associated with an increased incidence of cancer cell invasion into the portal vein, poorer histological differentiation, and more advanced TNM staging." (PMID 38927059, 2024). "We present evidence that HDAC inhibition increases cisplatin efficacy in eliminating cancer cells via the repression of HDAC1-Sp5, and the subsequent de-repression of proliferation inhibitor p21 manifests as inhibition of tumor clusters." (PMID 39001363, 2024). "MGCD0103 can modulate the molecular mechanism for several pathways in cells, such as inhibition of the PI3K/AKT pathway and suppression of HDAC1 enzyme activity in charge of many biological processes in the initiation and progression of cancer." (PMID 38645087, 2024). "HDAC1’s regulation of genes involved in key cancer pathways including drug resistance, cancer progression, and tumor suppression make it a strong candidate as a drug target." (PMID 37996815, 2023). "For instance, higher levels of CHD1L, HDAC1, MUTYH, NEIL3, POLR2L, RUVBL1, and SPP1 expression in cancer cells have been linked to higher levels of drug resistance to nelarabine, acridine, chlorambucil, dexrazoxane, cladribine, and other drugs." (PMID 37923899, 2023). "It was previously shown that HDAC1 is essential for cell proliferation and the transcription of core regulatory transcription factors (TFs), an essential factor in cancer growth." (PMID 37996815, 2023). "In the protein expression profile, HDAC1 expression in cancer tissues was higher than that in normal tissues in most of the protein expression categories." (PMID 36644230, 2023). "HDAC1 and HDAC2 are associated with various cellular events responsible for cancer growth and development." (PMID 36681835, 2023). "HDACs are divided into four classes, and class I HDACs (HDAC1, 2, 3, and 8) have attracted interest as therapeutic targets for cancer and some other diseases." (PMID 37076890, 2023). "HDAC1 also regulates expression of genes involved in resistance pathways in many cancers including apoptosis, DNA damage repair, metastasis, and EMT." (PMID 37996815, 2023). "CPT1AV2 knockdown upregulates the levels of HDAC1 and alters the expression of multiple cancer-related genes, including the downregulation of SERPINB2." (PMID 37884951, 2023). "Altered histone acetylation patterns in HDAC1 can result in epigenetic changes that contribute to cancer initiation and progression." (PMID 37888480, 2023).
cancer (continued). "Apigenin treatment inhibits class I histone dysentery and generates HDAC1 protein, both of which raise the level of acetylation of Ku70 in cancer cells and detach Bax, which ultimately leads to the death of cancer cells." (PMID 37843642, 2023). "For example, Entinostat (MS-275), which is currently in clinical trials for cancer treatment, selectively inhibits HDAC1, HDAC2, and HDAC3 with an IC50 of 0.54, 0.61, and 0.62 μM, respectively." (PMID 37759724, 2023). "Although the data showed that the differential multiples of HDAC1 were all within 2, HDAC1 mRNA overexpression ranked in the top 2%–6% in some cancer tissues." (PMID 36644230, 2023). "Whereas HDAC1 suppresses, p300 promotes TGFβ-induced EMT-associated phenotypic changes in three-dimensional organoids derived from mammary epithelial cells or carcinomas." (PMID 37414747, 2023). "At the same time, differential analysis of HDAC1 protein expression profile was performed to analyze the level of total protein and phosphorylated protein, as well as the expression of HDAC1 gene protein at the pan-carcinoma level (–7)." (PMID 36644230, 2023). "We propose that the dissociation or the maintenance of HDAC1 at the promoters of oncogenes or tumor suppressor genes in cancer cells is dependent on the presence of CREPT." (PMID 36230720, 2022). "RUNX3 is silenced by hypoxia both at the gene and protein levels in cancers by hypoxia-induced HDAC1 and/or G9a HMT." (PMID 36231060, 2022). "It appears that the high level of HDAC1 promotes tumorigenesis, therefore, the inhibition of HDAC1 induces cell cycle arrest, decreases viability, and increases apoptosis in cancer cells." (PMID 36230720, 2022). "High levels of Sp1 due to HDAC1/2/6 activities promote the division of cancer cells and G2/M progression." (PMID 35458763, 2022). "Current literatures have uncovered the relationship of HDAC1 or miR-200b with the resistance of cancer cells to several commonly used drugs in LAD, such as cisplatin, paclitaxel, and gefitinib." (PMID 35864549, 2022). "This study was designed to compare the effects of locally sourced BSO with those of pure TQ on the expression of the epigenetic complex UHRF1/DNMT1/HDAC1 and the related events in several cancer cells." (PMID 35566130, 2022). "The relative expressions of CREPT and HDAC1 in cancer tissue compared to the normal tissue were significantly correlated (R = 0.756, p = 0.00017)." (PMID 36230720, 2022). "The results of this experiment were found consistent with the study on the relationship between HDAC1 and cancer, which was observed high in abnormal proliferation." (PMID 35872845, 2022). "The pivotal role of SNAIL1 in association with HDAC1/HDAC2 and resulting in E-Cadherin repression in cancers has been documented." (PMID 35458763, 2022). "HDAC1/2 were considerable upregulated whereas HDAC11 was significantly downregulated in cancer tissues." (PMID 35359455, 2022). "In conclusion, our quantitative proteomics study provides a rich source of deacetylation targets of HDAC1 and small molecule inhibitors, which is essential to study acetylation dynamics in cancer cells and in general." (PMID 35954222, 2022). "Since both DNMT1 and HDAC1 are well-documented partners of the epigenetic reader UHRF1 in cancer cells, we studied the 24 h effect of BSO on the mRNA expression of the trimeric complex UHRF1, DNMT1 and HDAC1 in cancer cells." (PMID 35566130, 2022). "Further, to our knowledge, we are the first to report the role of the NANOG/HDAC1 axis in ICB therapy–refractory cancer." (PMID 35104240, 2022).
cancer (continued). "On the other hand, PKD3 enhances cancer cell invasion mainly through interacting with and suppressing the constitutive expression of histone deacetylase 1 (HDAC1), which binds to the uPA promoter and negatively regulates uPA transcription." (PMID 35805075, 2022). "In particular, HDAC1 is elevated in a variety of cancers, including gastric, colorectal, lung, and bladder cancers." (PMID 36230720, 2022). "The increasing role of the UHRF1/DNMT1/HDAC1/G9a complex in the epigenetic silencing of many TSGs in cancer supports the targeting of this multiprotein complex as a valuable approach for developing multitarget single epidrugs." (PMID 33922029, 2021). "It has been reported that silence of HDAC1 in cancer cells can either arrest at the G1 phase of the cell cycle or the G2/M transition, resulting in reduced number of mitotic cells, inhibited cell growth, and increased percentage of apoptotic cells." (PMID 34685648, 2021). "Largazole has received much attention due to its potent anti-proliferative activity against various cancer cells and substantial potency as a class I histone deacetylase (HDAC1) inhibitor." (PMID 34564150, 2021). "In cancer cells, SPHK2 associates with HDAC1 and HDAC2 in the transcription repressor complex, and S1P generated by SPHK2 binds to and inhibits HDAC1 and HDAC2, resulting in epigenetic regulation of gene expression." (PMID 34055895, 2021). "The dynamics of EGFR activity and possible crosstalk between several possible PTMs, including other phosphorylation sites, on HDAC1 warrant further study to characterize the intricacies of HDAC1 regulation in EGFR-driven cancers." (PMID 33976119, 2021). "Mechanistically, overexpression of HDAC1 recovered the cancer-inhibiting effects of miR-524-5p mimic or NEAT1 silence by deacetylation of tensin homolog deleted on chromosome ten (PTEN) and inhibiting AKT signal pathway." (PMID 34837887, 2021). "Histone deacetylase 1 (HDAC1) represents a deacetylase that has been implicated in the occurrence and development of various cancer in addition to exerting potential functions on cell functions." (PMID 33596966, 2021). "In contrast, the repression of Cdkn1a, Cdkn2a, Adam10, Pten and muscle-specific genes in different cancer cell lines or myoblasts cells depends on recruitment of HDAC1, hence, deacetylation of lysine residues in N-terminal tails of histones." (PMID 33731112, 2021). "HDAC1 mediated the effects of HOXA10 on cancer cell proliferation, migration, invasion, cell cycle progression, and apoptosis." (PMID 33596966, 2021). "While, despite massive studies, the upstream regulation of HDAC1 and its role in cancer stemness remain elusive." (PMID 33482915, 2021). "The bioinformatic analysis highlighted the importance of HDAC1 as the fundamental roles of its impacted pathways in stem cell maintenance, including Wnt, Notch, cell cycle, and transcriptional misregulation in cancer." (PMID 33482915, 2021). "This was because the SATB1-gene interaction network generated by FunRich software suggested that SATB1 was closely associated with other cancer-correlated genes, such as GATA3, HDAC1, and MTA2." (PMID 34604093, 2021). "Given its extensive contribution to maintaining cell survival, HDAC1 is therefore an important target to eliminate cancer cells by apoptosis." (PMID 33976119, 2021). "The role of HDAC1 in regulating processes such as cell cycle regulation, apoptosis, and DNA repair, among others, in cancer is well-established." (PMID 33976119, 2021). "This study thus explores a novel mechanism that SOX4 promotes cancer stemness and suggests that HDAC1 inhibition would be an effective strategy for eradicating human CSCs driven by SOX4 overexpression." (PMID 33482915, 2021).